DEFB130A (defensin beta 130A)
Description:
Antimicrobial host-defense peptide. Has an antiplasmodial activity.
Synonyms: DEFB-30; DEFB130; DEFB30; DEFB130L
Tractability: Antibody: UniProt places it where antibodies can reach, with high confidence; UniProt predicts a signal peptide or a membrane-spanning region; its Gene Ontology location is reachable by antibodies, with medium confidence.
Gene: Protein-coding gene on chromosome 8 (12,310,962 to 12,318,316, reverse strand). Ensembl gene ENSG00000232948.
Subcellular location: Secreted
Pathways (Reactome):
Immune System: Beta defensins; Defensins
Gene Ontology:
Molecular function: CCR6 chemokine receptor binding; chemoattractant activity
Biological process: cell chemotaxis; defense response to bacterium; defense response; positive chemotaxis
Cellular component: extracellular region
Homologues: Orthologues: macaque DEFB130B (94% identical), chimpanzee DEFB130B (92% identical), dog CBD130 (75% identical), rat Defb41 (66% identical), mouse Defb47 (62% identical). Paralogues in human: DEFB130B (100% identical), DEFB109B (43% identical), DEFB109C (43% identical), DEFB109D (42% identical), DEFB4A (20% identical), DEFB4B (20% identical).
Diseases named in the same sentence as DEFB130A in open-access papers:
DEFB130A is named in the same sentence as 1 disease in open-access papers, as found by Europe PMC text mining. Sharing a sentence is not in itself a finding about the gene and the disease.
DEFB130A shares sentences with these, for which no sentence is quoted: bacterial infections (1 paper).